FLI1 (Fli-1 proto-oncogene, ETS transcription factor)
Diseases named in the same sentence as FLI1 in open-access papers (continued):
Sharing a sentence is not in itself a finding about the gene and the disease.
bladder cancer (3 papers, 2019 to 2024). "We strengthened the association of FRA1 and FLI1 in bladder cancer cell’s invasion ability via employing IC-CHIP assay in different microenvironments and different knock-down conditions." (PMID 36805539, 2023). "The transcription factors FRA1 and FLI1 regulate cell migration and cell junction organization genes in muscle-invasive bladder cancer, and loss of these factors reduces cancer cell invasion, pointing toward a therapeutic avenue." (PMID 36805539, 2023). "Collectively our results highly suggest for the role of FRA1 and FLI1 in muscle-invasive capability of bladder cancer." (PMID 36805539, 2023). "Together, these results show the involvement of the FRA1 and FLI1 transcription factors in invasive capacity of bladder cancer cell lines with differential behavior in cell-free and muscle microenvironments." (PMID 36805539, 2023). "Further, the expression of FRA1 and FLI1 significantly correlates in bladder cancer cell lines (ρ = 0.58, p-value = 1.723e-3), collectively suggesting for the co-expression status of these two transcription factors and regulation of FLI1 expression by FLI1 itself and FRA1." (PMID 36805539, 2023). "Based on existing literature and our analysis, we hypothesized that FRA1 and FLI1 transcription factors can be the drivers of invasion to muscularis propria in bladder cancer." (PMID 36805539, 2023). "Additionally, considering the higher expression of FRA1 and FLI1 and their targets in bladder cancer with stages > T2, we propose that these two transcription factors can be critical players in the regulation of muscle-invasive bladder cancer cell lines." (PMID 36805539, 2023). "Thus, we suggest that FLI1 expression level might be a determining factor for treatment of bladder cancer patients with JQ1, which is shown to be quite effective for bladder cancer." (PMID 36805539, 2023).
breast tumor (3 papers, 2015 to 2020). "Using immunohistochemical staining, we found that FLI1 was significantly activated in breast tumor tissues as compared with adjacent normal tissues (red arrows)." (PMID 30537986, 2018). "We divided FLI1 expression scores into three groups (low, medium, and high) and examined the percentage rate of breast tumor metastasis between groups." (PMID 26156017, 2015). "Using immunohistochemically staining with FLI1 specific antibody, we found that FLI1 were significantly upregulated in breast tumor tissues as compared with adjacent normal tissues." (PMID 26156017, 2015). "Therefore, circ-FLI1 is thought to play a role in regulating breast tumor development, through the FLI1-stimulated promotion of the proliferation of malignant breast cells." (PMID 32878117, 2020).
chronic lymphocytic leukemia (3 papers, 2019 to 2024). "A drastic decrease in Fli-1 expression was also detected in B-chronic lymphocytic leukemia (B-CLL) cells isolated from 7 independent patients, 12 h post incubation with A661 or A665." (PMID 30741932, 2019).
diffuse large B-cell lymphoma (3 papers, 2021 to 2025). "This aligns with prior findings in diffuse large B-cell lymphoma models, where FLI-1 knockdown attenuated NF-κB1 (p50) and RelA (p65) expression." (PMID 40717962, 2025). "FLI-1 expression did not correlate with clinicopathological variables, such as demographic data or disease stage, in patients with plasmablastic lymphoma and diffuse large B-cell lymphoma." (PMID 38280044, 2024).
hemangioma (3 papers, 2025). A benign vascular lesion characterized by the formation of capillary-sized or cavernous vascular channels. "While hemangiomas exhibit dilated, blood-filled vascular channels lined by bland endothelial cells and stain positively for CD31, CD34, and FLI-1 (but are typically GLUT-1 negative in adults), lymphangiomas show similar spaces filled with proteinaceous fluid and are D2-40 and PROX1 positive." (PMID 40428263, 2025).
multiple myeloma (3 papers, 2020 to 2024). "FLI-1 expression can lead to diagnostic confusion, especially in small blue round cell tumors, such as lymphoblastic lymphoma, plasmablastic lymphoma, and plasma cell myeloma, when distinguishing tumors positive for CD99 and CD56 without CD3, CD20, or CD45." (PMID 38280044, 2024). "Interestingly, motif analysis of enhancer H3K27ac by ChIP-Seq implicated the Ets family TF FLI1 as an additional candidate for a regulator of cellular enhancers in PEL, reminiscent of the recently reported cooperation of FLI1 with IRF4 on SEs in multiple myeloma." (PMID 32843547, 2020). "Another Ets family TF, FLI1, has recently been shown to cooccupy sites with IRF4 in multiple myeloma." (PMID 32843547, 2020).
myeloid leukemia (3 papers, 2017 to 2024). A clonal proliferation of myeloid cells and their precursors in the bone marrow, peripheral blood, and spleen. "Indeed, the pleiotropic gene set was found to have an overrepresentation of regulators of myeloid leukemia: DOT1L, EP300, FLI1, GSE1, and MED24 (OR = 7.1; phypergeometric = 4 × 10−4)." (PMID 38308367, 2024).
nephritis (3 papers, 2010 to 2025). Inflammation of renal tissue. "Kidney endothelial cells produce significant inflammatory cytokines and are implicated in nephritis development, and we demonstrated that FLI-1 is highly expressed in renal endothelial cells." (PMID 37790939, 2023). "Future studies are aimed at investigating the impact of CPT on nephritis by inhibiting Fli-1 modulation of the CXCL10/CXCR3 axis." (PMID 37790939, 2023). "In vitro constructs in this long size range (23 to 28 repeats) exhibited weaker activation of the Fli1 promoter in P/R assays, suggesting that lower Fli1 expression may be protective against nephritis and contribute to serositis." (PMID 21087477, 2010). "Together, the combined results strongly suggest an important role for FLI-1 in modulating the CXCL10-CXCR3 axis and thus, in promoting nephritis, further supporting FLI-1 as potential therapeutic target." (PMID 37790939, 2023).
non-small cell lung carcinoma (3 papers, 2017 to 2022). A group of at least three distinct histological types of lung cancer, including non-small cell squamous cell carcinoma, adenocarcinoma, and large cell carcinoma. "Recently, it was reported to be upregulated in cisplatin-resistant non-small cell lung cancer, and its knockdown inhibited cancer cell growth/cisplatin resistance by downregulating FLI1 expression." (PMID 36360233, 2022). "Using immunohistochemical staining, we found that FLI1 was significantly upregulated in SCLC tissues, compared to that in non-small cell lung cancer (NSCLC) and normal lung tissues (p < 0.01)." (PMID 28410216, 2017).
platelet disorders (3 papers, 2022 to 2025). "Specialized adhesion assays assess disorders of primary hemostasis caused by abnormal platelet properties, including in patients with inherited platelet disorders such as FLI-1 mutations and Hermansky-Pudlak syndrome (HPS)." (PMID 37596311, 2023).
prostate adenocarcinoma (3 papers, 2022 to 2025). "The consortium published the status of ERG, ETV1, ETV4, and FLI1 fusions in the cBioportal database (dataset: Prostate Adenocarcinoma (TCGA, Cell 2015)) for 333 samples." (PMID 37349736, 2023).
renal cell carcinoma (3 papers, 2021 to 2022). "Therefore, in vivo toxicity profile and anti-angiogenic potential of promising benzenesulphonyl hydrazone derivative possessing antiproliferative activity, particularly against renal cell carcinoma, were assessed in our study using zebrafish models (AB and Tg(fli1: EGFP))." (PMID 36355480, 2022). "Immunohistochemistry indicated FLI-1(+), CD99(+), Vimentin(+), CyclinD1(+), WT-1(+), EMA(+), Bcl2(-), Ki-67(+) 60%, CD56(-), CK(-), CD34(-), Desmin(-), and SMA(-), which suggested that renal clear cell sarcoma may not rule out renal cell carcinoma." (PMID 33859949, 2021).
renal failure (3 papers, 2022 to 2024). "Early work has demonstrated that Fli1 transgenic mice developed a high incidence of immunological renal disease and ultimately died of renal failure caused by tubulointerstitial nephritis and immune-complex glomerulonephritis." (PMID 36768203, 2023). "Moreover, MBG signaling through Na/K-ATPase is directly responsible for suppression of Fli1 and the stimulation of cardiac fibroblasts to produce increased amounts of collagen, thus triggering cardiac fibrosis seen with experimental renal failure." (PMID 36768203, 2023).
Alzheimer disease (2 papers, 2024 to 2025). A progressive, neurodegenerative disease characterized by loss of function and death of nerve cells in several areas of the brain leading to loss of cognitive function such as memory and language. "Similarly, we found that Fli-1 in brain pericyte contributes to the inflammatory response in the brain in Alzheimer’s disease, where inhibition of Fli-1 reduced inflammatory mediators such as IL-6 in the hippocampus." (PMID 39862276, 2025). "Furthermore, our previous findings indicated that FLI1 contributes to the neuroinflammation in Alzheimer’s disease." (PMID 39140108, 2024).
astrocytoma (2 papers, 2017 to 2024). "In the present study, a high Fli-1 expression level was associated with poor prognosis and a high WHO grade in patients with astrocytoma; in other words, Fli-1 expression associates strongly with survival in this patient population." (PMID 28418872, 2017). "A high level of Fli-1 expression was detected in high-grade astrocytomas and was associated with poor prognosis, and both the univariate and multivariate analyses identified an association of Fli-1 with the overall survival duration." (PMID 28418872, 2017). "Fli-1 protein expression in astrocytoma tissue samples were detected via immunohistochemistry, and potential correlations between clinical parameters and Fli-1 expression were assessed in patients with astrocytoma." (PMID 28418872, 2017). "Fli-1 shows promise as a potential prognostic biomarker and therapeutic molecular target for astrocytoma patients." (PMID 28418872, 2017). "Fli-1 knockdown attenuated the proliferation, migration, and invasion of astrocytoma cells and downregulated the expression of Ki-67, VEGF, and cyclin D1." (PMID 28418872, 2017). "The levels of Fli-1 expression in the glia cell line SVGq12 and astrocytoma cell lines GBM8401, GBM8901, U87MG, and G5T were analyzed via western blotting." (PMID 28418872, 2017). "A multivariate analysis revealed that the WHO grade and Fli-1 protein expression were independent factor of prognostic factors of patients with astrocytoma." (PMID 28418872, 2017). "In high grade (WHO grade III/VI) astrocytoma, a high level of Fli-1 expression correlated significantly with poor overall survival (P = 0.027)." (PMID 28418872, 2017). "In our study, Fli-1 was detected in the nuclei of astrocytoma tissues, as well as GBM8401, GBM8901, U87-MG, and G5T cells." (PMID 28418872, 2017). "In low grade (WHO grade II) astrocytoma, a high level of Fli-1 expression correlated significantly with poor overall survival (P = 0.003)." (PMID 28418872, 2017). "A Kaplan–Meier analysis and subsequent log-rank analysis confirmed the correlation between Fli-1 expression and survival in astrocytoma patients; specifically, a high level of Fli-1 expression correlated significantly with poor overall survival (P < 0.001)." (PMID 28418872, 2017). "The present study aimed to elucidate the clinical role of Fli-1 in astrocytoma." (PMID 28418872, 2017). "The nuclear transcription factor Fli-1 has been shown to increase cellular proliferation and tumorigenesis in many types of cancer; however, previous reports have not described a correlation between clinical outcomes and Fli-1 in astrocytoma patients." (PMID 28418872, 2017). "The cellular localization of Fli-1 was evaluated in astrocytoma cells." (PMID 28418872, 2017). "Therefore, the present study aimed to validate the clinical role of Fli-1 in patients with astrocytoma." (PMID 28418872, 2017). "However, in our study, Fli-1 siRNA-mediated knockdown inhibited the proliferative, migration, and invasion abilities of astrocytoma cells." (PMID 28418872, 2017). "In summary, Fli-1 was expressed in the nuclei of astrocytoma cells." (PMID 28418872, 2017). "However, no previous studies have identified a correlation between Fli-1 protein expression and the clinical parameters associated with astrocytoma." (PMID 28418872, 2017). "In addition, Fli-1 silencing inhibited proliferation, migration, and invasion and led to the downregulation of Ki-67, VEGF, and cyclin D1 expression in the astrocytoma cells." (PMID 28418872, 2017).
atherosclerosis (2 papers, 2018 to 2024). A disease characterized by the build-up of fatty material and calcium deposition in the arterial wall resulting in partial or complete occlusion of the arterial lumen. "FLI1 regulates the expression of metalloproteases (MMP-1, MMP-3, and MMP-10) and the pro-inflammatory cytokine IL-10; therefore, during chronic inflammatory conditions, such as AR and atherosclerosis, FLI1 down-regulation could attenuate tissue damage associated with inflammatory responses." (PMID 39767648, 2024).
Autoimmunity (2 papers, 2018 to 2019). The occurrence of an immune reaction against the organism's own cells or tissues. "Interestingly, Fli1 deficiency in epithelial cells spontaneously induces the fibrosis of skin, esophagus, and lungs as well as autoimmunity." (PMID 29544542, 2018). "Several genes, such as TREX1, FLI1, EVI5, IL1RAPL1, are known for their role in autoimmunity, with EVI5 being an established MS risk gene, whereas others, such as CBFB, OPCML and KMT2A, are involved in lymphoproliferative disorders (OMIM)." (PMID 30541027, 2019). "Importantly, heterozygous deficiency of both Fli1 and KLF5 results in the development of all three features of SSc, including autoimmunity, vasculopathy, and fibrosis." (PMID 29544542, 2018).
colitis (2 papers, 2022 to 2025). Inflammation of the colon. "This study aimed to evaluate Lumefantrine’s efficacy in a DSS-induced murine colitis model and elucidate its mechanism, focusing on FLI-1 targeting and NF-κB pathway modulation in intestinal epithelial cells." (PMID 40717962, 2025). "Consistently, our DSS-induced colitis model showed increased colonic FLI-1 expression, which was effectively suppressed by Lumefantrine treatment." (PMID 40717962, 2025). "Lumefantrine ameliorates experimental colitis through FLI-1-dependent inhibition of the NF-κB pathway, demonstrating high repurposing potential as an IBD therapeutic." (PMID 40717962, 2025). "To extend our study beyond allogeneic responses, we used the classical syngeneic T cell transfer model of colitis to determine whether Fli-1 contributes to T cell–mediated gut damage." (PMID 36074578, 2022).
colorectal adenoma (2 papers, 2019 to 2022). An adenoma that arises from the colon or rectum. "FLI1 was hypermethylated in colorectal adenomas and carcinomas, and plasma DNA methylation of FLI1 showed great clinical relevance in differing CC subtypes and tumor stages." (PMID 35647294, 2022). "In previous reports, FLI1 hypermethylation in tumor tissues was observed in GC, colorectal adenomas, and carcinomas." (PMID 31675985, 2019).
erythroblastic leukemia (2 papers, 2017 to 2021). "The potential oncogenic nature of Fli-1 was previously demonstrated in erythroblastic leukemia, wherein Fli-1 was shown to induce the proliferation of differentiation-arrested erythroblasts with longer survival of Fli-1 expressing with BCL2 expression." (PMID 28418872, 2017). "NKX2-4 is aberrantly expressed in erythroblastic leukemia cell line OCI-M2 and represses FLI1, while NKX2-3 is aberrantly expressed in megakaryoblastic leukemia cell line ELF-153 and activates FLI1." (PMID 34768865, 2021).
glomerulonephritis (2 papers, 2020 to 2023). A renal disorder characterized by damage in the glomeruli. "While overexpression of Fli-1 results in lupus-like glomerulonephritis, homozygous Fli-1 gene deletion (Fli-1−/−) results in fetal demise in association with neural tube hemorrhage." (PMID 32183259, 2020).
Jacobsen syndrome (2 papers, 2008 to 2009). A multiple congenital anomaly/intellectual disability contiguous gene syndrome caused by partial deletion of the long arm of chromosome 11. "The megakaryocytic defects in 14 Jacobsen syndrome patients were mapped to a minimal region of overlap in 11q that includes the FLI1 gene, thus suggesting that dysmegakaryopoiesis in these patients may be caused by hemizygous loss of FLI1." (PMID 20003197, 2009).
lymphedema (2 papers, 2025). Excess fluid collection in tissues, causing swelling. "The impact of loss of Erg and Fli1 function on lymphatic development in mice is consistent with FOXC2 mutations in lymphedema-distichiasis syndrome or ERG gene variants underlying primary lymphedema in humans." (PMID 41460562, 2025).
metastatic melanoma (2 papers, 2019 to 2021). A melanoma that has spread from its primary site to another anatomic site. "Overall, FLI-1 expression was higher in metastatic melanoma than in primary tumors and was associated with aggressive behavior." (PMID 34449584, 2021). "Interestingly, one case of metastatic melanoma with loss of conventional markers expressed FLI-1 diffusely." (PMID 34449584, 2021).
oral squamous cell carcinoma (2 papers, 2019 to 2023). "In oral squamous cell carcinoma (OSCC), FLI1 served as a prediction marker for radiotherapy resistance." (PMID 31231464, 2019).
small cell carcinoma (2 papers, 2014 to 2022). A neuroendocrine carcinoma composed of small malignant cells which are often said to resemble "oat cells" under the microscope. "Hence, a wider range of immunohistochemical markers, including chromogranin and TTF-1 to support a diagnosis of small cell carcinoma, and CD99, vimentin, or FLI1 for PNET should be used for the differential diagnosis." (PMID 25475214, 2014).
thyroid cancer (2 papers, 2016 to 2022). "In addition to well-known BRAF, RAS, and RET mutations, NGS technology facilitated detection of new somatic alterations in thyroid cancer such as MITF, MDM2, JAK3, FLI1, IDH1 etc., all in which the significance of thyroid cancer has not been delineated yet." (PMID 27871285, 2016).
Wilms tumor (2 papers, 2013 to 2025). An embryonal neoplasm characterized by the presence of epithelial, mesenchymal, and blastema components. "Wilms tumors usually strongly express WT1 and fail to express membranous CD99, FLI-1, or nuclear NKX2.2." (PMID 40978053, 2025).
Allergy (1 paper, 2024). An allergy is an immune response or reaction to substances that are usually not harmful. "In addition to cancer, AM is used to treat lupus erythematosus allergy/asthma, and this is consistent with the role of FLI1 in these inflammatory diseases." (PMID 39769192, 2024).
basal cell carcinoma (1 paper, 2013). A carcinoma involving the basal cells. "Since GLI1 has been shown to drive expression of FOXM1 in basal cell carcinoma, there is an appealing logic to the hypothesis that EWS/FLI1 indirectly targets FOXM1 through deregulation of GLI1." (PMID 23365673, 2013).
brain haemorrhages (1 paper, 2025). "To confirm these findings, we used a zebrafish double transgenic reporter for ECs and erythrocytes [Tg(fli1:EGFP)/Tg(gata1a:DsRed)] to evaluate spike-induced brain haemorrhages in vivo." (PMID 40406995, 2025).
breast angiosarcoma (1 paper, 2022). A malignant vascular neoplasm arising from the breast. "It is confirmed as primary breast angiosarcoma by immunostaining in the tumor tissue for CD31, CD34, and FLI-1." (PMID 36555675, 2022).
cardiac hypertrophy (1 paper, 2020). "Given the importance of ANKRD1 in regulating fibrosis and cardiac hypertrophy, further studies are required to assess if its induction in response to low Fli1 in Mo/Mø contributes to their fibrogenic effects." (PMID 32508810, 2020).